SCGB1C2 (secretoglobin family 1C member 2)
Tractability: Antibody: UniProt places it where antibodies can reach, with medium confidence; UniProt predicts a signal peptide or a membrane-spanning region; its Gene Ontology location is reachable by antibodies, with medium confidence.
Gene: Protein-coding gene on chromosome 17 (137,569 to 139,067, forward strand). Ensembl gene ENSG00000268320.
Subcellular location: Secreted
Gene Ontology:
Molecular function: protein binding
Cellular component: extracellular region
Genetic constraint (gnomAD): Loss-of-function variants: 3 observed, 2.29 expected, observed/expected ratio (o/e) 1.31, 90% interval 0.52 to 1.91. That is too few expected variants to judge how well the gene tolerates losing a copy. Missense variants: 27 observed, 37.3 expected, observed/expected ratio (o/e) 0.72, 90% interval 0.53 to 1. Synonymous variants: 12 observed, 16.9 expected, observed/expected ratio (o/e) 0.71, 90% interval 0.45 to 1.15.
Homologues: Orthologues: macaque SCGB1C1 (93% identical), dog SCGB1C1 (79% identical), guinea pig Scgb1c1 (76% identical), rat Scgb1c1 (74% identical), mouse Scgb1c1 (71% identical). Paralogues in human: SCGB1C1 (99% identical), SCGB1A1 (27% identical).